CD34 (CD34 molecule)
Diseases named in the same sentence as CD34 in open-access papers (continued):
Sharing a sentence is not in itself a finding about the gene and the disease.
acute myeloid leukemia (continued). "Similarly, RAB27B is upregulated in CD34+ acute myeloid leukemia (AML) CSCs and to plays a role in the stemness of these cells." (PMID 38765006, 2024). "In acute myeloid leukaemia (AML), B7H4 is expressed on leukaemia-initiating cells and enriched CD34+ AML cells." (PMID 39061159, 2024). "Regorafenib suppresses acute myeloid leukemia (AML) engraftment in vivo and sensitizes CD34+ AML cells in the peripheral blood and spleen." (PMID 38953895, 2024). "Bonnet and Dick were the first to identify a subpopulation of human acute myeloid leukemia (AML) cells, marked by CD34+ CD38, which were able to induce malignancy in transplanted mice." (PMID 39547513, 2024). "Bone marrow evaluation confirmed the diagnosis of acute myeloid leukemia (AML), with myeloid blasts positive for CD33, CD34, CD13, and MPO on flow cytometry, and a significant monocytic component (M4 according to French-American-British (FAB) classification)." (PMID 39830569, 2024). "CD34 + CD38− acute myeloid leukemia (AML) cells were used to identify CSCs." (PMID 36675306, 2023). "In myelodysplastic syndromes (MDS), neoplastic myeloblast (CD34+CD13+CD33+ cells) numbers often increase over time, leading to secondary acute myeloid leukemia (AML)." (PMID 37729123, 2023). "Similarly, transplantation of acute myeloid leukemia (AML) patient-derived CD34+CD38− cells results in the establishment of an AML-like disease including the development of leukemic blasts." (PMID 35990601, 2022). "Interestingly, in acute myeloid leukemia (AML) patients, CD34+ hematopoietic progenitors show SNF2H upregulation, which can be drug-inhibited to release terminal-differentiation while sparing normal hematopoiesis." (PMID 34070411, 2021). "The continued relevance of the CD34/CD38 marker combination is exemplified in two recently published studies regarding the prognostic significance of a high CD34+/CD38- stem cell burden in patients with myelodysplastic syndromes and acute myeloid leukemia." (PMID 33878141, 2021). "In acute myeloid leukemia (AML), Bonnet and Dick first detected cells having similar characteristics to normal hematopoietic stem cells with the same markers (CD34+ and CD38−) that were much more prone to developing leukemia, which were referred as leukemic stem cells (LSCs) or CSCs." (PMID 34051847, 2021). "To understand how this contributes to the development of acute myeloid leukemia (AML), we compared the nuclear proteome and transcriptome of AML blasts with normal human CD34+ cells." (PMID 31611628, 2020). "Although CD34+CD38-6, 7, CD133+8 and CD44+CD24-9-11 have been widely used as CSCs markers in human acute myeloid leukemia, brain tumor and breast cancer respectively." (PMID 31892981, 2020). "Acute myeloid leukemia (AML) cell lines and primary samples display reduced BUBR1 expression compared with normal CD34+ bone marrow precursors and acute lymphoblastic leukemia (ALL) blasts." (PMID 31771633, 2019). "The first evidence for CSCs came in a 1994 study, which proved that one CD34+/CD38-cell from human acute myeloid leukemia (AML) could reinitiate leukemia in mice." (PMID 31277278, 2019). "Here we have identified that miR-125a-5p upregulation plays a critical role in the differentiation of human acute myeloid leukemia HL-60 and NB4 cells as well as of normal human CD34+-HPCs towards neutrophils or neutrophil-like cells." (PMID 31523391, 2019). "Thus we analyzed its expression in CD34-enriched population of human hematopoietic stem cells (HSCs), CD34-enriched population of human liver cells, human hepatocytes, human prostate epithelial cells, and the CD34-positive human acute myelogenous leukemia cell line KG-1." (PMID 31877678, 2019). "In the 1990s, the theory of a hierarchical organization within tumors was introduced in acute myeloid leukemia (AML), identifying leukemia-initiating cells via their expression of a CD34++CD38− phenotype." (PMID 29922594, 2018).
acute myeloid leukemia (continued). "In acute myeloid leukemia (AML), activation of Hh signaling has been shown in several human AML cells, especially primary CD34+ leukemic cells." (PMID 30423843, 2018). "Subsequently, the researchers successfully isolated the CD34+, CD38−, and CD90− phenotypes of leukemia cells from acute myelocytic leukemia (AML) tissues by immunofluorescence and flow cytometry." (PMID 30344611, 2018). "Bone marrow immunophenotypic analyses revealed 23% blasts; positivity for CD34, HLADR and CD33; and negativity for CD7, CD19, CD10, CD117, CD36 and CD15, characterizing acute myeloid leukemia (AML), FAB classification M4." (PMID 28832804, 2018). "We employed mass spectrometry methods to analyze the proteome of the cytosolic and the membrane fraction of CD34 and CD123 co-expressing FACS-sorted leukemic progenitors from five patients with acute myeloid leukemia." (PMID 29439554, 2018). "We first measured the effect of BA on the AHR expression in different acute myeloid leukemia (AML) cell lines, and the primary CD34 positive hematopoietic stem cells (CD34+) were used as a control." (PMID 29212263, 2017). "PDCD4 expression was induced in NB4 and HL-60 acute myelocytic leukemia (AML) cell lines, primary human promyelocytic leukemia (AML-M3) cells, and CD34+ hematopoietic progenitor cells in the presence of all-trans retinoic acid." (PMID 27852288, 2016). "In acute myeloid leukemia (AML) cells, the CD34+CD15− population increases following AhR suppression by a block in differentiation rather than by an increase in proliferation." (PMID 27243009, 2016). "Human CSCs/CICs were first isolated from acute myeloid leukemia (AML) as CD34+CD38- cells." (PMID 27415781, 2016). "One such cell line is the cytokine-dependent CD34+ MUTZ-3 monocytic acute myeloid leukemia (AML) cell line, which has previously been used as a sustainable model to study human DC differentiation and maturation (interstitial DC-like [IDC] and Langerhans cells [LC]) in vitro." (PMID 26252775, 2015). "Taken together, our data supported that constitutive activation of the ERK/MSK/Sp1 axis (as shown by phosphorylation of the pathway components) was required for over-expression of survivin in CD34+ AML patients, and finally permitting the evolution to the “Seed cell” in acute myeloid leukemia." (PMID 25890196, 2015). "We performed transcriptome analysis on primitive CD34+ acute myeloid leukemia (AML) cells (n = 46), their more differentiated CD34− leukemic progeny, and normal CD34+ bone marrow cells (n = 31) and focused on differentially expressed genes involved in adhesion and migration." (PMID 25360637, 2014). "However, CSCs have been being isolated from more and more cancers, since first discovered in the acute myeloid leukemia (AML) by using CD34++/CD38- biomarkers." (PMID 24564919, 2013). "Flow cytometry results showed CD34 98%, HLA-DR 98%, CD13 96%, CD33 99%, CD11 97% with negativity for CD10 and CD22 in 71% cells gated, thus confirming acute myeloid leukemia." (PMID 22928122, 2012). "Acute myelogenous leukaemia was observed to be positive for CD117, CD34 and cMPO." (PMID 39968161, 2025). "CSCs were first identified in acute myeloid leukemia (AML) after transplanting isolated CD34+/CD38− cancer cells into non-obese diabetic/severe combined immunodeficient (NOD/SCID) mice." (PMID 41190163, 2025). "Furthermore, Anti-CD47 antibody therapy disrupts the signal on CD34+CD38- leukemic stem cells, enhancing macrophage-mediated phagocytosis and achieving durable remissions in preclinical Acute Myeloid Leukemia (AML) models." (PMID 40881675, 2025). "Peripheral CD34+ acute myeloid leukemia (AML) cell clones express 5-LO while healthy CD34+ cells do not." (PMID 38575760, 2024). "They found ERG immunopositivity in 15 of 16 (94%) acute myeloid leukemias/myeloid sarcomas, including four out of five (80%) CD34-negative/CD117-negative acute myeloid leukemias/myeloid sarcomas." (PMID 38933637, 2024).
acute myeloid leukemia (continued). "Acute myeloid leukemia (AML) is a clonal hematopoietic disorder characterized by the malignant transformation and abnormal proliferation of bone marrow-derived, self-renewing stem cells, or CD34+ CD38− myeloid progenitors." (PMID 37623484, 2023). "Past studies have also shown that inhibition of SF3B1 previously evaluated in the clinic against MDS, acute myeloid leukemia (AML), and chronic monomyelocytic leukemia (CMML) blocks the growth of leukemia cells and exhibits relatively low toxicity toward normal CD34+ hematopoietic progenitors." (PMID 35061527, 2022). "In particular, a decline in DC/MC of the myeloid lineage (CD33+/CD34+) is associated with disease relapse: in patients transplanted for acute myeloid leukemia (AML) and myelodysplastic syndrome (MDS), CD34+ PBMC MC was found to be an independent predictor of relapse and inferior survival." (PMID 34950586, 2021). "VPS34-IN1 was found to induce apoptosis in nine acute myeloid leukemia (AML) cell lines but not in normal CD34+ hematopoietic cells." (PMID 34681622, 2021). "In AML (acute myelogenous leukemia) patients, the ratio of four major WT1 isoforms A : B : C : D was shown as 17 : 23 : 24 : 31% while the ratio of these isoforms was 10 : 16 : 7 : 39% in normal CD34+ cells." (PMID 33110919, 2020). "In the early nineties, Dick and colleagues observed that most subtypes of acute myeloid leukemia (AML) could be engrafted reliably in immunodeficient mice and that leukemic engraftment could only be initiated from CD34+CD38− fractions." (PMID 31317205, 2019). "For example, in acute myeloid leukemia (AML), CSCs populations are CD34(+) CD38(−)." (PMID 29907133, 2018). "It has been demonstrated that brain, colon, prostate and lung CSCs bear the antigen CD133, while ovarian CSCs are CD24+ and CD133+, acute myeloid leukemia stem cells are CD34+ and CD38−, head and neck CSCs are CD44+, B-precursor acute Lymphocytic leukemia CSCs are CD34+, CD38+ and CD19+." (PMID 26184171, 2015). "They found that acute myeloid leukemia (AML) CD34+ cells with virtually absent CXCR4 expression were able to engraft, but the cells with high expression of CXCR4 did not." (PMID 21294880, 2011). "A CSC model was first suggested in Acute Myeloid Leukemia (AML), where only a rare population of CD34+ CD38- cells in the peripheral blood collected from AML patients could engraft in immunodeficient mice and recapitulate morphological features of the original malignancy." (PMID 24212622, 2011). "Furthermore, it is specifically expressed on primary acute myeloid leukaemia (AML) blasts and in a leukemic CD34 + CD38-stem cell compartment, which has highlighted its potential as a diagnostic and therapeutic target in AML." (PMID 20934454, 2011). "Similarly, the enhancer activity of h-FLT3 was supported by more robust H3K27ac ChIP-seq signals in MLL-r acute myeloid leukemia (AML) cells (MOLM13, MOLM14, and MV4;11 cells) as compared with non-MLL-r AML cells (IMSM2, HEL, K562, SET2, U937, and HL60 cells) and normal CD34+ cells 35–37." (PMID 38016946, 2023). "Unlike most cancers, SCLC can in fact express CD34; it follows that alteration in the CD34 state through serotonylation may potentially alter hypermethylation patterns in promoter CpG islands in acute myeloid leukemia." (PMID 36831672, 2023). "The CSC population has been identified in acute myeloid leukemia (AML) as cells showing CD34 and CD38 expression or co-expression of both markers, CD34/CD38." (PMID 37626893, 2023). "CSCs were first identified in acute myeloid leukemia (AML); the study demonstrated that AML CSCs with the phenotype CD34+ CD38− constituting approximately 0.1–1% of the tumor population, can generate AML in mice." (PMID 36768150, 2023). "(E) IRAK4 expression in sorted HSCs (Lineage –ve, CD34+, CD38−) cells from MDS/acute myeloid leukemia (AML) cases (N=9) and controls (N=5)." (PMID 36040792, 2022).
acute myeloid leukemia (continued). "The cancer stem cell (CSC) paradigm emerged from investigating a subpopulation of less-differentiated CD34+/CD38- cells possessing stem cell-like renewal ability and robust malignant-initiating capacity in acute myeloid leukemia (AML)." (PMID 36627897, 2022). "NFE2L2 is constitutively active in human acute myeloid leukemia (AML) cells, and these cells possess greater constitutive nuclear levels of NFE2L2 than normal control CD34+ cells." (PMID 35056649, 2022). "In approximately 15% of patients with acute myeloid leukemia (AML), total and phosphorylated EGFR proteins have been reported to be increased compared to healthy CD34+ samples." (PMID 34650910, 2021). "By using fluorescence activated cell sorting (FACS) based on CD34 and CD38 (CD34+ CD38−) surface marker expression, John Dick isolated the first CSCs from acute myeloid leukemia (AML)." (PMID 30728463, 2019). "Enforced expression of MLL-AF4 alone is incapable of transforming human CD34+ cord blood, and mouse models expressing MLL-AF4 alone are not fully representative of the human disease, instead producing B-cell lymphomas acute myeloid leukemia (AML), or precursor B-ALLs (pre-B-ALLs)." (PMID 23352661, 2013). "miR-17-92 is also overexpressed in MLL (mixed lineage leukemia)-rearranged acute myeloid leukemia (AML) and acute lymphoblastic leukemia (ALL), and in CD34+ chronic myeloid leukemia (CML)." (PMID 21698185, 2011). "Several studies have characterized the nature of FLT3 expression in human and murine cells and identified its importance in early hematopoiesis (CD34+cells), and also shown that FLT3 expression can be high in hematologic malignancies such as acute myeloid leukemia (AML)." (PMID 39200232, 2024). "To determine if the presence of VSLSLCs and/or SLSLCs is not limited to HL-60, we analyzed the levels of CD34, CD45, and CD56 markers in two other myeloid leukemia cell cultures: KG1a—Acute Myeloid Leukemia (AML) and K562—Chronic Myeloid Leukemia (CML during blast crisis)." (PMID 38067224, 2023). "CSCs were first reported in liquid tumors, such as leukemias, with CD34+/CD38− cancer cells capable of initiating and promoting tumorigenesis in immunodeficient mice injected with cells derived from Acute Myeloid Leukemia (AML) patients." (PMID 36776295, 2023). "Furthermore, ATX is copiously expressed in CD34+ HSCs and FLT3-ITD+ acute myeloid leukemia (AML) cells." (PMID 32188052, 2020). "In the myelodysplastic syndrome (MDS), the chronic myelomonocytic leukemia (CMML), and the acute myeloid leukemia (AML), increased PD-L1 levels were observed on CD34+ cells, whereas stroma/non-blast cellular compartment was positive for PD-1." (PMID 31185600, 2019). "Primary acute myeloid leukemia (AML) blasts have a range of expression levels of β-catenin, apparently not correlating with CD34 expression, indicating that the link between β-catenin downregulation and myeloid differentiation is uncoupled in leukemia." (PMID 29050252, 2017). "Immunohistochemical markers revealed that the tumour was negative for acute myeloid leukaemia (AML), anti-pan-cytokeratin AE1/AE3 (Cytokeratin AE1/AE3), cluster of differentiation 34 (CD34) and S100." (PMID 35919234, 2022). "Acute myeloid leukemia patients with cGVHD had received HSCT grafts containing lower levels of monocytes (p = 0.005) and higher levels of “CD34+relat” (p = 0.01) than those without cGVHD." (PMID 27917176, 2016). "Cancer stem cells (CSCs), firstly presented in 1997, when only CD34+CD38− gave rise to patients with acute myeloid leukemia (AML) in nonobese diabetic/severe combined with immunodeficient mice, could induce hematopoietic malignancies demonstrated by Bonnet and Dick." (PMID 27057280, 2016). "In contrast to other tested antigens co-expressed on chronic myeloid leukemia (CML) LSCs, acute myeloid leukemia (AML) LSCs and normal HSCs, CD26 is the only marker which is not present in CD34+/CD38− normal stem cells." (PMID 39000199, 2024).
acute myeloid leukemia (continued). "A bone marrow biopsy was conducted, which showed myelodysplasia with an excess blast of 13% and hypercellular marrow (80%), and flow cytometry showed positivity for CD34 positive myeloblast and CD117 erythroblast ruling in MDS, but evidence of acute myeloid leukemia (AML) was ruled out." (PMID 34285848, 2021). "Acute myeloid leukemia (AML) patients who developed aGVHD were transplanted with higher levels of effector CD3+ T, CD19+ B, and CD123+ dendritic cells than AML patients without aGVHD, whereas grafts with a high CD34+ content protected against aGVHD." (PMID 27917176, 2016). "In a separate study, heteroclitic-variants of CD33, a cell surface glycoprotein restricted to myeloid lineage cells, effectively generated acute myeloid leukemia (AML)-specific CTL, that did not lyse or inhibit the proliferation of normal CD34+ progenitor cells." (PMID 26257743, 2015).